MDM2 (MDM2 proto-oncogene)
Diseases named in the same sentence as MDM2 in open-access papers (continued):
Sharing a sentence is not in itself a finding about the gene and the disease.
tumor (continued). "The results showed that G1 had a lower aggressive pathological composition ratio, MDM2 and Ki67 expression, larger tumor size, and higher tumor microenvironment (TME) level compared to G2." (PMID 40407808, 2025). "Its overexpression has been identified as a biomarker for HPD, with studies showing that MDM2 suppresses anti-tumor immunity by reducing T cell activation and promoting an immunosuppressive environment." (PMID 41170373, 2025). "By regulating key processes such as cell cycle, DNA repair, signal transduction, and hypoxia response, these enzymes can both promote tumor development as oncogenes (e.g. MDM2) and inhibit cancer as tumor suppressor genes (e.g. BRCA1, VHL)." (PMID 40276056, 2025). "Recently, Zeng and collaborators conducted a comprehensive review highlighting the crucial role of MDM2 in shaping the immune microenvironment, facilitating tumor immune evasion, and driving hyperprogression during immunotherapy." (PMID 41515979, 2025). "Its underlying mechanisms involve suppressing MMP-2 expression via the MDM2-mediated degradation pathway, reducing tumor vascular invasion, and enhancing cisplatin chemotherapy sensitivity." (PMID 40115255, 2025). "Originally identified as an oncogene amplified in murine tumor cells, MDM2 has since emerged as a central player in tumorigenesis." (PMID 41170373, 2025). "This possible positive feedback loop between NF-kB and MDM2, ultimately leading to tumor cell progression, should also be investigated in MM, as it offers therapeutic targeting opportunities, as described in the literature." (PMID 41303785, 2025). "Compared with that in control tumor samples, knockout of MDM2 transcripts led to reduced ac4C modification and MDM2 downregulation." (PMID 41316475, 2025). "In CRC, MDM2 overexpression drives tumor progression and therapeutic resistance while compromising tumor immunogenicity through downregulation of MHC class I expression and promotion of immune evasion." (PMID 41246348, 2025).
tumor (continued). "This leads to cell cycle arrest, apoptosis, and significant growth inhibition of human tumor xenografts in nude mice, paving the way for novel cancer therapies targeting MDM2." (PMID 41515979, 2025). "In this study, we found that the biodegradable MDM2-siRNA complex had a suppressive effect on MDM2-mRNA in cancer cells and tumor growth of peritoneal dissemination." (PMID 41009451, 2025). "The first human trial of ALRN-6924 confirmed its anti-tumor activity with mild side effects, particularly a lower myelosuppressive effect was observed compared with the MDM2 inhibitors." (PMID 39960347, 2025). "We believe inhibition of MDM2 activity can improve the long-term prognosis of tumor patients undergoing general anesthesia surgery." (PMID 40335909, 2025). "In BC, particularly TNBC, TGF-β pathway alterations involve multiple molecular players, including SOX4, MDM2, and circDISP3, ultimately promoting tumor growth and metastasis." (PMID 40804731, 2025). "Through rescue experiments combining NFATc1 knockdown with MDM2 overexpression, we observed a partial reversal of the NFATc1 knockdown-induced suppression of both cell proliferation and tumor growth." (PMID 41203626, 2025). "Given its widespread involvement in tumor development and progression, MDM2 is also recognized as a prognostic biomarker, with high expression levels linked to advanced disease stages and treatment resistance." (PMID 41170373, 2025).
tumor (continued). "MDM2 proliferative targets include the activation of E2 F1 transcriptional activity and suppression of tumor suppressive effects of Rb through binding to Rb and inhibiting the function of Rb-E2 F repressor." (PMID 40580306, 2025). "MDM2, an E3 ubiquitin ligase of PD-1, can promote PD-1 degradation through ubiquitination of disaccharidased PD-1 and enhance the anti-tumor effect of T cells." (PMID 39759114, 2025). "In the other 50% of cancers, it retains wild-type activity but its tumor suppressor activity is significantly inhibited by an endogenous ubiquitin protein called murine double minute 2 (MDM2)." (PMID 40339040, 2025). "MDM2 amplification has been shown to trigger functional autoimmune responses, thereby promoting the expansion of functional autologous tumor-specific T cells." (PMID 40575167, 2025). "To improve the therapeutic potential of peptides that interfere with MDM4 binding to MDM2, we demonstrated the tumor‐suppressive activity of a short peptide (Pep3S), which is composed of the last five amino acids of the MDM4 protein." (PMID 40022459, 2025). "Among these, the proteins encoded by MDM2 and CDK4 play a role in cell cycle regulation and are considered driving genes for this tumor type." (PMID 40674962, 2025). "In summary, combining MDM2 inhibitors with ICI therapy offers a promising strategy to enhance anti-tumor efficacy and bypass resistance, especially in cases where MDM2 monotherapy is suboptimal." (PMID 41515979, 2025).
tumor (continued). "Tumor cells can acquire resistance to MDM2 inhibitors, which are currently under clinical evaluation." (PMID 39222276, 2024). "MDM2 inhibition can also modulate the expression of MHC-I and MHC-II in tumor cells in different ways, which seems to suggest that MDM2 inhibition is an excellent way to avoid resistance to ICIs." (PMID 39263534, 2024). "If the remission is either stable or we will see further reduction in tumor size, we intend to evaluate the patient for enrollment in a clinical trial testing an Mdm2 inhibitor." (PMID 38656400, 2024). "The aim of this targeted review was to evaluate and synthesise evidence on the epidemiology of BTC and its subtypes in different geographic regions and on the frequency of MDM2 amplifications in BTC tumours." (PMID 39302603, 2024). "Although CD4 + T cells can recognize the epitope of tumor cell MDM2 and directly eliminate tumor cells, immune tolerance still develops." (PMID 38281981, 2024). "Here, we reviewed the role of MDM2 in regulating the immune microenvironment, tumor immune evasion, and hyperprogression during immunotherapy." (PMID 39263534, 2024). "DLPS02, derived from its parental DDLPS tumor, featured chromosome 12q13–q15 amplification with duplicated MDM2 gene." (PMID 39117615, 2024). "The core tumor suppressor p14ARF, in turn, can bind both MDM2 and ARF-BP1, inhibiting their ubiquitin ligase activity)." (PMID 39770524, 2024). "As the most often amplified gene in a wide range of human malignancies, MDM2’s significance in tumor growth cannot be underestimated." (PMID 38263255, 2024). "A strategy to broaden the use of immunotherapy would be to inhibit MDM2/X and enhance the immunogenicity of the tumor, increasing the infiltration of lymphocytes into tumors, reactivating the immune response." (PMID 38784022, 2024).
tumor (continued). "At the same time, transwell assay showed that tumor invasiveness was enhanced after overexpression of MDM2, and the addition of Rosiglitazone significantly reduced the ability of the tumor cell migration." (PMID 39258786, 2024). "The impact of AMG-232 on anticancer immunity was further evaluated, and recent research suggests that it enhances the sensitivity of high MDM2-expressing tumor cells to T-cell-mediated killing." (PMID 38281981, 2024). "The preclinical and clinical studies have supported the viability of the MDM2 inhibitors-related approach to mediate anti-tumor activity." (PMID 39144622, 2024). "Despite demonstrating potent anti-tumor cell proliferation effects in preclinical experiments, the clinical efficacy of MDM2 inhibitors has been somewhat disappointing." (PMID 39263534, 2024). "Mechanistically, MDM2 acts as an oncogene in the development of malignancies and can promote tumor cell proliferation and metastasis, directly contributing to disease progression." (PMID 38281981, 2024). "In this review, we delve into the diagnosis and therapeutic implications of neoplasms with genetic alterations involving the chromosomal region 12q13-15, mainly MDM2, CDK4, and GLI1." (PMID 38275873, 2024). "The mechanism of MDM2 involves its role as an oncogene during the development of malignancy, and MDM2 can promote both metastasis and tumor cell proliferation, which indirectly leads to disease progression." (PMID 38281981, 2024). "In mouse tumor models, NVP-CGM097, an MDM2 inhibitor, led to an elevation in the dendritic cell count, the proportion of T cells in tumors and tumor-draining lymph nodes, and the ratio of CD8 + T cells to regulatory T cells in tumors." (PMID 38281981, 2024). "MDM2 showed a strong nuclear expression whereas CDK4 showed only weak expression in some tumor cell nuclei." (PMID 38656400, 2024). "Given its importance in promoting tumorigenesis, MDM2 has become a highly sought-after tumor therapeutic target." (PMID 38263255, 2024). "The combination of these two peptides induces a stronger tumor-killing effect, suggesting that a single MDM2 peptide has a poorer effect on tumor suppression than peptides targeting multiple sites." (PMID 39263534, 2024). "In recent years, several MDM2 inhibitors have been found that can be combined with ICB to improve the tumor treatment effect of ICB." (PMID 39253578, 2024). "The use of a combination therapy involving a VEGF inhibitor (bevacizumab) and an MDM2 inhibitor (Nutlin-3) has been shown to significantly inhibit tumor proliferation and angiogenesis." (PMID 38281981, 2024).